HIF1A (hypoxia inducible factor 1 subunit alpha)
Diseases named in the same sentence as HIF1A in open-access papers (continued):
Sharing a sentence is not in itself a finding about the gene and the disease.
hepatocellular carcinoma (continued). "In hepatocellular carcinoma (HCC), aberrant expression of hypoxia-inducible factor 1 α (HIF1α) and increased aerobic glycolysis metabolism are drivers of resistance to therapy with the multi-kinase inhibitor Sorafenib." (PMID 34272356, 2021). "In this follow-up study, we could demonstrate that the inhibition of CRM1 by Selinexor decreases the intranuclear HIF-1α protein level in human osteosarcoma and human hepatocellular carcinoma cells accompanied by an enhanced radiation response in both cell lines." (PMID 33856525, 2021). "Given that HIF-1α is a transcription factor that contributes to the angiogenesis and growth of tumors in the hypoxic microenvironment, it is reasonable to speculate that CaMK2 can promote the growth and survival of hepatocellular carcinoma cells." (PMID 34193145, 2021). "HIF-1α is degraded under normoxic condition via the proteasome pathway but is stabilized under hypoxia.To date, a series of studies have reported that HIF-1α expression could be an important predictor of tumor prognosis, including for hepatocellular carcinoma, cervical carcinoma and lung cancer." (PMID 33732648, 2021). "The positive feedback between SENP1 and HIF-1α can improve the stem cell characteristics of hepatocellular carcinoma (HCC) and promote the occurrence of HCC." (PMID 33791211, 2021). "Furthermore, mRNA expression of hexokinase 2 (HK II), which catalyzes the phosphorylation of glucose to glucose-6-P, corelates with HIF-1α protein in hepatocellular carcinoma cells and metastatic liver cancer, and HK II and HIF-1α protein expression co-localized in these cancer cells." (PMID 34360716, 2021). "The accumulation of excess HIF1-α protein enhances the transcription of downstream target genes, which in turn enhances the malignant biological behaviors such as proliferation, invasion and metastasis, and neovascularization of hepatocellular carcinoma cells, leading to tumor progression." (PMID 34420039, 2021). "In addition, in hepatocellular carcinoma, circRNA_0046600 could upregulate HIF-1α by sponging miR-640 to promote cancer progression." (PMID 32014012, 2020). "Furthermore, we knockdowned HIF1α in mouse hepatoma cell line (Hepa1-6)." (PMID 27716621, 2016). "Activation of HIF-1α under hypoxic condition promoted hepatocellular carcinoma (HCC) to EMT and induced drug resistance by increasing the expression of MDR1." (PMID 27455225, 2016). "However, it is not known whether bufalin could exert the antimetastatic effect by modulating HIF-1α expression in hepatocellular carcinoma." (PMID 26958938, 2016). "In hepatocellular carcinoma (HCC), HIF-1α activation following extended hypoxia strongly correlates with an aggressive phenotype, metastasis and poor prognosis." (PMID 26047481, 2015). "Pilot studies have evaluated the correlation between hypoxia-inducible factor-1α (HIF-1α) overexpression and clinical outcome in hepatocellular carcinoma (HCC) patients." (PMID 23799043, 2013). "Recent studies have not only identified the vascular endothelial growth factor (VEGF) to be overexpressed in hepatocellular carcinoma, but also that the transcription factor HIF-1α plays a central role in HCC progression and angiogenesis." (PMID 18651980, 2008). "The involvement of circular RNAs (circRNAs) have been well‐documented in various cancers, including hepatocellular carcinoma (HCC); however, their regulatory roles in HIF‐1α‐mediated tumorigenesis remain largely unclear." (PMID 41541658, 2026). "BPA also impacts liver cancer, as seen in human hepatocellular carcinoma (Hep3B), where BPA induces degradation of hypoxia-inducible factor 1-alpha (HIF-1α) through the lysosomal pathway, thereby disrupting the cellular response to hypoxia." (PMID 41440754, 2025). "Paradoxically, in sorafenib-resistant hepatocellular carcinoma (HCC) models, FASN orchestrates nuclear accumulation of HIF1α to drive SLC7A11 transactivation, thereby conferring ferroptosis resistance." (PMID 40890129, 2025).
hepatocellular carcinoma (continued). "In Bel-7404 and Huh7 cells, it inhibits the HIF-1α-mediated glycolytic pathway, thereby suppressing cell proliferation and cancer progression in the TME of hepatocellular carcinoma patients." (PMID 41585262, 2025). "OTUD6B suppressed hepatocellular carcinoma metastasis, involving a feedback loop consisting of OTUD6B, pVHL, and HIF-1α; CircPTPN12 bolstered the assembly of the PDLIM2/OTUD6B complex and inhibited hepatocellular carcinoma progression by PDLIM2/NF-κB pathway." (PMID 40651961, 2025). "In hepatocellular carcinoma, EGCG inhibits the expression of HIF-1α and VEGF, two molecules with important roles in tumor angiogenesis." (PMID 40218859, 2025). "NUSAP1 can bind to c-Myc and HIF-1α, not only directly enhancing glycolysis and lactate production in hepatocellular carcinoma (HCC) cells but also increasing NUSAP1 lactylation levels through a positive feedback loop, further promoting the proliferation of HCC cells." (PMID 40860191, 2025). "HIF1A and CA9 were activated in TGFβ‐induced hepatoma cell line MHCC‐97H and were inhibited by sanguinarine." (PMID 40417738, 2025). "Treatment with EGCG or the EGCG derivative Y6 was found to significantly inhibit tube formation in hepatocellular carcinoma cells and angiogenesis in transplanted tumors, likely via the downregulation of the MAPK/ERK1/2 and PI3K/AKT/HIF-1α/VEGF pathways." (PMID 40218859, 2025). "In hepatocellular carcinoma cell line (HepG2), ABCF1 K430la facilitates tumor progression by stimulating the expression of HIF1A and its downstream molecules, enhancing lactate production." (PMID 40994548, 2025). "Similarly, USP14 maintains HIF-1α stabilization via its deubiquitination activity in hepatocellular carcinoma (HCC)." (PMID 39757165, 2025). "Recently, it has been shown that in hepatocellular carcinoma (HCC) tissues, FABP5 induced HIF-1α expression and activity, and their expression levels were associated with poor prognosis." (PMID 40016284, 2025). "RhoA and Rac1 have been demonstrated to stabilize the HIF-1α protein, suggesting the possible cross-talk between small G-proteins and HIF pathways in hepatocellular carcinoma." (PMID 39941828, 2025). "Currently, only one study has reported the anti-hepatocellular carcinoma effect of inotodiol, which demonstrated that inotodiol is capable of markedly suppressing the growth of HCC cells, and the target of its action was HIF-1α." (PMID 39879230, 2025). "Another study conducted in hepatocellular carcinoma cells reported that METTL3 also had a binding relationship with HIF-1α mRNA to promote the m6A modification and expression of HIF-1α." (PMID 38233403, 2024). "HIF-1α also plays a crucial role in the glycolytic reprogramming of TAMs; consequently, inhibition of HIF-1 and HIF-2 has been shown to suppress hepatocellular carcinoma growth and enhance the efficacy of anti-programmed death 1 (PD1) therapy." (PMID 39227970, 2024). "Piezo-CAP, a cold atmospheric plasma technology, effectively suppresses hepatocellular carcinoma by inducing apoptosis and autophagy through targeting redox balance, glycolysis, and the PI3K/AKT/mTOR/HIF-1α signaling pathways." (PMID 39315094, 2024). "The discovery that BMP9-ID1 can activate the expression of HIF-1α and VEGFA supports a new strategy for developing targeted therapies for hepatocellular carcinoma." (PMID 39619441, 2024). "As an upstream signaling molecule in hepatocellular carcinoma, PLAGL2 can regulate the expression of HIF-1α." (PMID 39102510, 2024). "The HIF‐1α/miR‐210‐3p/CPEB2 signaling axis regulated the EMT and metastasis of hepatocellular carcinoma." (PMID 39149855, 2024). "In hepatocellular carcinoma cells (HCC), miR-1307-3p increased proliferation and invasion under hypoxia conditions by downregulating DAB2IP to activate AKT/mTOR and increase HIF-1α expression." (PMID 38902547, 2024).
hepatocellular carcinoma (continued). "For example, in hepatocellular carcinoma, the glycolytic enzyme pyruvate kinase M2 (PKM2), induced by hepatoma cell-derived fibronectin 1, can regulate macrophage glycolysis in a HIF-1α-dependent manner." (PMID 37491279, 2023). "The expression and activation of HIF-1α and FGF11 inevitably needs to be considered for evaluating prognosis and therapeutic options for HBV-derived hepatocellular carcinoma." (PMID 37646922, 2023). "In a recent investigation on hepatocellular cancer, COMMD10 was also discovered to bind and inhibit HIF-1α, and it has to be determined if additional members of the COMMD protein family have comparable effects." (PMID 36776284, 2023). "The three signaling molecules formed the HIF-1α/STAT3/VEGF signal transduction pathways, which played an important role in the occurrence and development of hepatocellular carcinoma." (PMID 37333486, 2023). "External validation confirmed positive correlations for FAP and angiogenesis receptors FLT1, KDR, and KIT as well as HIF1A and ETS1 in hepatocellular carcinoma but also in metastatic prostate cancer (Dream Team cohort)." (PMID 36672341, 2023). "Moreover, sorafenib, a molecular targeted drug for the treatment of advanced hepatocellular carcinoma in clinic, has also been demonstrated to alleviate hepatic fibrosis induced by CCl4 by triggering ferroptosis of HSCs via the Hypoxia-inducible factor 1 alpha (HIF-1α)/SLC7A11 pathway." (PMID 38086792, 2023). "Suppression of HIF1α by meloxicam could exert antiproliferative efficacy in hepatocellular carcinoma (HCC) and lead to caspase-reliant apoptosis of HCC in hypoxia." (PMID 37174078, 2023). "To elucidate the mechanism by which RPLP2 influences aerobic glycolysis in hepatoma cells and subsequently regulates proliferation, we employed lentivirus-mediated overexpression of HIF-1α (HIF-1α-OE) in Hep3B cells." (PMID 38052785, 2023). "In hepatoma cells, EGCG inhibits hypoxia-induced HIF-1α accumulation through PI3K/Akt and ERK1/2 pathways, and subsequently causes a strong decrease in VEGF expression." (PMID 37292151, 2023). "Analysis from Wang and his coauthors illustrated that hypoxia-induced lncRNA MAPKAPK5-AS1 contributed to the growth and spread of hepatocellular carcinoma cells through the MAPKAPK5-AS1 and HIF1A signaling loop." (PMID 38057853, 2023). "For example, HIF-1α and the IL-6-JAK-STAT3 signaling pathways were significantly activated and accelerated hepatocellular carcinoma growth after longer hepatic pedicle clamping followed by major hepatectomy." (PMID 37628777, 2023). "Recent studies have shown that HIF1α can induce EMT, which leads to metastasis and poor prognosis of hepatocellular carcinoma (HCC)." (PMID 37790761, 2023). "In HepG2 hepatocellular carcinoma cells, OA was found to facilitate survival through the FABP5–hypoxia-inducible factor-1 alpha (HIF-1α) axis, which plays a pivotal role in response to hypoxic stress." (PMID 37373069, 2023). "In hepatocellular carcinoma cells, in response to hypoxia, nuclear YAP binds to HIF-1α to maintain the stability of HIF-1α and promote the transcription of glycolytic genes." (PMID 38274792, 2023). "This is because Jmjd1a expression has previously been reported to be induced by HIF-1α in several cell lines (e.g. endothelial and cancer cell lines), and Tet2 is also regulated by HIF-1α in HepG2 hepatocellular carcinoma cells." (PMID 37158274, 2023). "While in Hepatocellular carcinoma (HCC), OTUD6B decreases HIF-1α accumulation in HCC cells under hypoxia via directly interacting with pVHL to reduce its ubiquitination and proteasomal degradation, thereby inhibiting HCC cell metastasis." (PMID 37752518, 2023). "Simvastatin can inhibit the HIF-1α/PPAR-γ/PKM2 axis and suppress PKM2-mediated glycolysis, resulting in decreased tumor cell proliferation and increased apoptosis in a xenograft hepatocellular carcinoma (HCC) mouse model." (PMID 35685487, 2022).
hepatocellular carcinoma (continued). "For hepatocellular carcinoma, AQP9 suppresses hepatocellular carcinoma cell growth and metastasis via distinct pathways, including HIF-1α, PI3k/Akt, Wnt/β-catenin, and FOXO1." (PMID 35972604, 2022). "The key molecule responsible for angiogenesis in hepatocellular carcinoma cells is a vascular endothelial growth factor (VEGF);both hypoxia-inducible factor 1α (HIF-1α) and pro-inflammatory NF-κB upregulate the expression of VEGF." (PMID 36614030, 2022). "Several reports have indicated how hypoxia-induced miRNAs regulated the switch between HIF-1α and HIF-3α in human endothelial cells and how their regulatory feedback circuit enhanced tumor metastasis in hepatocellular carcinoma." (PMID 36277475, 2022). "For instance, HIF1α directly bond to the promoter of KDM4A-AS1 and upregulated it expression in hepatocellular carcinoma 36, and HIF1α upregulated PVT1 transcription by binding to its promoter region in pancreatic cancer." (PMID 35414787, 2022). "In hepatocellular carcinoma HepG2 and HCC97Hcells, caffeic acid (20 μM) reducedJNK-1-mediated stabilization of HIF-1α and, in this way, decreased the level of active HIF-1α available." (PMID 36614030, 2022). "For instance, upregulation of hepatitis B virus X-interacting protein (HBXIP) positively promotes expression of the m6A methylase METTL3, resulting in enhanced HIF-1α expression and maintenance of high levels of glycolysis, thus promoting malignant proliferation of hepatocellular carcinoma (HCC)." (PMID 35794625, 2022). "As a significance downstream factor in the HIF1α pathway, ZEB1 plays a critical role in EMT in hepatocellular carcinoma." (PMID 35589690, 2022). "CA might also perform hepatocellular carcinoma (HCC) cells’ angiogenesis by decreasing the JNK-1 phosphorylation through the reduction of HIF-1α activation." (PMID 35355732, 2022). "In human hepatoma cell lines, hypoxia increased both DNL and fatty acid uptake through HIF-1α and -2α dependent mechanisms." (PMID 35313531, 2022). "Further, Y6, a derivative of EGCG, downmodulates HIF-1α and ABCB1 levels in doxorubicin-resistant hepatocellular carcinoma cells." (PMID 34575983, 2021). "High-expressed HIF1A may be strongly correlated to the poor prognosis of hepatocellular carcinoma (HCC) patients." (PMID 34477476, 2021). "By reducing STAT3 and HIF-1α levels, sulforaphane also diminishes VEGF expression, exerting anti-angiogenic effects in hepatocellular carcinoma." (PMID 34575983, 2021). "Excitingly, we revealed a novel mechanism by which hepatocellular carcinoma tissues tolerate hypoxic adversities and maintain sustained malignant biological behavior through the modulation function of USP14 on HIF1-α-mediated transactivation." (PMID 34420039, 2021). "Quercetin inhibited proliferation via induction of HIF-1α expression and HIF-1 activity in HepG2 hepatoma cells under normoxia and hypoxia." (PMID 33401572, 2021). "Under hypoxic conditions, SET7/9 has been shown to mediate the survival of various cancer cells against hypoxic stress by promoting HIF-1α protein stability and enhancing HIF-1-mediated gene transcription in osteosarcoma, hepatoma, and renal cell carcinoma." (PMID 34201935, 2021). "Activation of the PI3K/Akt/HIF-1α pathway contributes to hypoxia-induced EMT and chemoresistance in hepatocellular carcinoma." (PMID 33170151, 2020). "It has been reported that chromobox 4, a SUMO E3 ligase, can enhance the SUMOylation of HIF-1α at K391 and K477 through SIM-dependent way in hepatocellular carcinoma (HCC) and improve the expression of VEGF and angiogenesis." (PMID 33273928, 2020).
hepatocellular carcinoma (continued). "As CPS1-IT1 expression is significantly decreased in hepatocellular carcinoma tissue and cell lines this results in promotion of epithelial-mesenchymal transition (EMT) and increased metastatic potential in vivo through HIF-1α activation." (PMID 32640630, 2020). "Through transcriptome sequencing of human hepatocellular carcinoma (HCC) samples, six genes—TSC1, TSC2, PABPC3, HIF1α, RB1CC1 (ATG17), and RPS6KA3 (RSK2)—were found to be associated with HBV infection." (PMID 33059752, 2020). "Metformin has an antitumor angiogenesis effect by suppression of HER2/HIF-1α/VEGF pathway and inhibits angiogenesis of hepatocellular carcinoma." (PMID 31470817, 2019). "Through the results of western blotting and immunohistochemical staining, we also found that the protein expression of HIF-1α and VEGF in hepatoma tissue greatly reduced." (PMID 30911540, 2019). "Recently, research has revealed that in hepatocellular carcinoma, it exerts its anti-angiogenesis effect though suppressing the STAT3/HIF-1α/VEGF signaling network." (PMID 30871059, 2019). "The expression level of HIF-1α was determined in hepatocellular carcinoma (HCC) cells." (PMID 29881400, 2018). "Similarly, in hepatocellular carcinoma (HCC), hypoxia and HIF-1α increases NIPP and EZH2 levels, an effect that then results in augmented invasive and metastatic potential." (PMID 30510924, 2018). "In colorectal and hepatocellular carcinoma, HIF1α was found to compete with TCF-4 for direct binding to β-catenin enhancing transcriptional HIF1α activity." (PMID 29422917, 2017). "We retrospectively evaluated the expression of HIF-1α and LOXL2 as well as the prevalence of VM among a cohort of 201 hepatocellular carcinoma specimens." (PMID 28449718, 2017). "HIF1α has been shown to promote HCV replication in hepatocytes and to potentiate the migration of hepatoma cells." (PMID 28493839, 2017). "Together, these data indicate that the regulation of HIF-1α and Nrf2 by As(III) contributes to the angiogenic responses of endothelial cells and the colony-forming properties of hepatoma cells." (PMID 27286880, 2016). "VEGF is closely associated with the development and metastasis of HCC, and inhibition of IGF-1 or HIF-1α may be an promising target for hepatocellular carcinoma." (PMID 25663870, 2015). "In contrast, silibinin is a nontoxic flavonoid that is able to inhibit hypoxia-dependent HIF-1α accumulation and to inhibit HIF-1 transcriptional activity in HeLa and hepatoma cells." (PMID 26146622, 2015). "The whole study suggests that miR-20b, HIF-1α, and VEGF serve as a potential therapeutic agent for hepatocellular carcinoma." (PMID 26612965, 2015). "Taken together, we show that HDAC activity regulates HIF-1α translation, with HDACis such as SAHA representing a potential novel approach for the treatment of hepatocellular carcinoma." (PMID 25166596, 2014). "To investigate the mechanism underlying the knockdown of miR-210 mediated tumor growth delay, we analyzed protein expression of HIF-1α gene and miR-210 targeted MNT, EFNA3 and AIFM3 genes in human hepatoma xenograft by Western blot." (PMID 23618526, 2013). "In contrast, hypoxia and HIF-1α induced expression of ENO1 and LDHA in another human cancer cell line, HEP3B hepatoma cells." (PMID 23866118, 2013). "To investigate the mechanism underlying the knockdown of miR-210 mediated growth delay in SMMC-7721/Lv-anti-210 xenograft, we analyzed protein expression of HIF-1α, MNT, EFNA3 and AIFM3 genes in human hepatoma xenograft by Western blot." (PMID 23618526, 2013). "Our group has previously studied the invasion mechanisms derived from hypoxia/HIF-1α in hepatocellular carcinomas and pancreatic cancer in which MMPs and HGF/HGFA/c-Met activation occur downstream of the hypoxia/HIF-1α axis and act to increase cancer invasion." (PMID 24216696, 2013).